CD4 (CD4 molecule)
Diseases named in the same sentence as CD4 in open-access papers (continued):
Sharing a sentence is not in itself a finding about the gene and the disease.
psoriasis (continued). "Further we analyzed the expression of the four diagnostic genes screened by the two machine algorithms in 10 major immune cells and found that CCNE1 was elevated in CD4+ T cells as well as neutrophils in psoriasis lesions, and ARHGEF28 was elevated in mast cells." (PMID 38803495, 2024). "It reproduces several aspects of psoriasis including acanthosis and parakeratosis, neutrophil infiltration in the epidermis, and activation of the IL-23–IL-17 axis resulting proliferation of IL-17A-producing CD4+ T cells in the lesional skin." (PMID 38312837, 2024). "Our findings clearly show that CD4+ and CD8 T-cell panels can cause psoriasis." (PMID 38558803, 2024). "Moreover, miRNAs impact the function of immune cells involved in the pathogenesis of psoriasis, such as CD4+ T cells, regulatory T (Treg) cells, dendritic cells, and Langerhans cells." (PMID 38655054, 2024). "Similar to CD8+ TRM cells, skin CD4+ TRM cells play a role in the relapse of psoriasis in humans." (PMID 39193473, 2024). "The development of psoriasis depends on the differentiation of naïve CD4+ T cells into Th17 cells." (PMID 38139173, 2023). "Therefore, the study of the proportion of Foxp3 + CD4 + Treg cells represents an entry point for the investigation of the pathogenesis of psoriasis and the treatment with targeted agents." (PMID 37506136, 2023). "The accumulation of MDSCs in the skin is more significant compared to healthy individuals, suggesting their potential involvement in the long-term inflammatory process of psoriasis through the modulation of CD4+ T cell differentiation, especially promoting Th17 cell differentiation." (PMID 38239345, 2023). "In addition, there is a decrease in the activity of CD4+ lymphocytes, and an increase in the production of IL-4, which has an anti-inflammatory effect in psoriasis." (PMID 36675592, 2023). "These alterations in the skin demonstrate the functions of the CD4+ helper T cells in psoriasis." (PMID 37942312, 2023). "Regarding patients suffering from both psoriasis and HS, the IL-23/Th17 axis was found to be the common denominator, as experimental studies stated that IL-23 is overexpressed by macrophages in lesions of HS in addition to CD4+ T cells producing IL-17." (PMID 38003284, 2023). "Moreover, the application of a targeted FFA4 agonist resulted in substantial alleviation of IMQ-triggered psoriasis-like skin aberrations and inhibited the transition of CD4+ T cells into Th17 cells." (PMID 38035065, 2023). "CD4+ Th17 cells and their cytokine pathway may be the key to understand a possible correlation between ILDs and psoriasis." (PMID 37763769, 2023). "Notably, our study found that BaP stimulation in exosomes from PBMCs of patients with psoriasis triggered inflammatory reactions involving changes in psoriatic cytokine expression and Th1/Th17 CD4+ T-cell distribution in recipient PBMCs from healthy controls." (PMID 38288335, 2023). "In addition to Th1 cells and cytotoxic T cells, Th17 cells are known to play essential roles in the pathogenesis of psoriasis, but the frequencies of CD4+ IL-17+ cells observed in our study were too low to draw reliable conclusions." (PMID 38173716, 2023). "Additionally, BaP affects exosomes from peripheral PBMCs of psoriasis patients, triggering exacerbated Th1/Th17 cytokine production and Th1/Th17 CD4+ T-cell differentiation in recipient peripheral PBMCs from normal controls." (PMID 38288335, 2023). "CD4+ T cells, particularly the Th1, Th17, and Th22 subsets, play a significant role in psoriasis." (PMID 38239345, 2023). "The percentage of CD4+T cells was increased in the blood of psoriasis patients." (PMID 35069008, 2022). "We found etanercept could decrease the Th17/Treg ratio in CD4+ T cells and induce macrophages polarize to M2 in psoriasis mice." (PMID 36444619, 2022).
psoriasis (continued). "The same strategy of halting the elevated pro-inflammatory cytokine in psoriasis may work with IL-21, which is majorly secreted by CD4+ T cells, Th17 cells and T follicular helper cells." (PMID 35203707, 2022). "However, compared with psoriasis without arthritis, T cells CD4 memory activated were increased in the psoriasis with osteoarticular involvement, while T cells CD4 memory resting decreased." (PMID 35371093, 2022). "Results showed that this preparation can improve psoriasis symptoms by down-regulating the expression of IL-17A, Ki67, and CD4+T. This experiment provides great scalability for researchers to treat psoriasis, avoid first-pass effects, and increase the concentration of targeted drugs." (PMID 35409158, 2022). "When the percentages of T17 cells in T-cell subsets were directly compared using human psoriasis skin single-cell RNA sequencing (scRNA-seq) data, T17 cells constituted 2.7% of the CD4+ T-cell cluster, 1.3% of the CD8+ T-cell cluster, 2.4% of the CD161+ T-cell cluster and 0.5% of the Treg cluster." (PMID 36110854, 2022). "In psoriasis patients, CD4+ Trm cells were mainly located in the epidermis of skin lesions." (PMID 36118867, 2022). "Also, myeloid cells are important producers of TNF-α, iNOS, and IL-23, which promote the production of IL-17A by CD4+ T cells, and contribute to cardiovascular comorbidities related to psoriasis." (PMID 36741386, 2022). "Interestingly, studies in synovial fluid from patients with PsA have shown increased CD4+/IL-17+ T-lymphocytes and decreased CD4+/IL-22+ T-lymphocyte, suggesting their different role in the pathogenesis of PsA vs. psoriasis." (PMID 35722498, 2022). "Furthermore, small extracellular vesicles released from psoriatic keratinocytes transfer miR-381-3p to CD4+ T cells, which induces the polarization of Th1 and Th17 cells and eventually contributes to psoriasis development." (PMID 36726968, 2022). "After UMSC transplantation (UMSCT), the frequencies of Tregs and CD4+ memory T cells were significantly increased, and the frequencies of T helper (Th) 17 and CD4+ naive T cells were significantly decreased in peripheral blood (PB) of psoriasis patients." (PMID 35927231, 2022). "Indeed, topical application of maresin-1 showed anti-inflammatory effects in an imiquimod-induced psoriasis mouse model by inhibiting the production of IL-17A by γδTCR mid+ and CD4+ cells in the skin through repression in IL-23 receptor expression." (PMID 35886846, 2022). "In psoriasis, effector CD4+ T lymphocytes contribute to inflammation and tissue damage." (PMID 36096831, 2022). "Studies in immunodeficient mice have shown that CD4+ is among the first promoters of psoriasis." (PMID 35335319, 2022). "In addition, CD4+ cell activation causes in situ recall and CD8+ cell stimulation, which are also involved in the pathogenesis of psoriasis." (PMID 35335319, 2022). "Among them, Macrophages.M2 and Mast.cells.resting presented high levels of infiltration in control groups, while T.cells.gamma.delta, Dendritic.cells.activated, T.cells.CD8, T.cells.CD4.naïve, and NK.cells.resting exhibited high levels of infiltration in psoriasis groups." (PMID 35729678, 2022). "CD4+ T cells in lesional skin produce similar amounts of IL-17 compared to psoriasis." (PMID 35967358, 2022). "Studies have shown that methylation changes of CD4+ T cells affect the polarization of CD4+ T cells, which may be the pathogenesis of psoriasis." (PMID 35711463, 2022). "Furthermore, CD8+ T cells producing IL-17 and CD4+ T cells producing IL-22 remain in resolved lesions and can be stimulated to produce psoriasis-related cytokines even after treatment with biologics such as infliximab for several years." (PMID 34445713, 2021). "miR-138 is significantly downregulated in CD4+ T cells from psoriasis patients." (PMID 33718413, 2021). "H. pylori may potentiate psoriasis by inducing CD4+ T cell responses, while C. Albicans elicits antibody and Th17 responses." (PMID 34639182, 2021).
psoriasis (continued). "Moreover, the IL-17+CD4+T cells population in psoriasis groups was significantly inhibited by DHA administration." (PMID 34483908, 2021). "A parallel miRNA network exists in CD4+ T cell subsets from psoriasis patients." (PMID 33718413, 2021). "Furthermore, a group of IL-17A+/Foxp3+/CD4+ triple-positive cells were identified in the lesional skin of psoriasis patients." (PMID 34975883, 2021). "The expression of microRNA-210 is increased in circulating CD4+ T cells from patients with psoriasis, and this increase may contribute to the reduced Foxp3 mRNA and protein levels in the patients’ CD4+ T cells." (PMID 34501328, 2021). "One hypothesis could be that the psoriasis patient group with a high level of CXCL10 is more prone to develop arthritis due to its chemoattractant properties on CXCR3+ CD4+ and CD8+ T cells." (PMID 34127053, 2021). "microRNA-210 binds to the 3′-untranslated region of Foxp3, and the overexpression of microRNA-210 inhibits Foxp3 expression in CD4+ T cells from healthy controls, whereas inhibition of microRNA-210 increases Foxp3 expression in CD4+ T cells from patients with psoriasis." (PMID 34501328, 2021). "CD4+Foxp3+ Treg cells are involved in the pathogenesis of psoriasis." (PMID 34768720, 2021). "Heatmap of 22 immune cells indicated that psoriasis was positively correlated with activated memory CD4+T cell, activated myeloid DC, neutrophils, and T follicular helper (Tfh) cells, while negatively correlated with T regulatory cell (Tregs) and activated mast cell." (PMID 33732554, 2021). "Besides, miR-210 overexpression leads to abnormal cytokine expression, namely increased IFN-γ/IL-17 and decreased IL-10/TGF-β production, in CD4+ T cells from patients with psoriasis." (PMID 33718413, 2021). "In addition, the antimicrobial peptide LL37 has been reported as a putative autoantigen in psoriasis with the potential to promote secretion of Th17 cytokines by reactive CD4+ T cells." (PMID 33171607, 2020). "Psoriasis, a common chronic inflammatory skin disease, is mediated by the pathological cross-talk between epidermal keratinocytes and immune cells, including infiltrating CD4+T cells, CD8+T cells, and Mo-MDSCs." (PMID 32382290, 2020). "In psoriasis, CD4+ cells are the main source of IL-17 and IL-22." (PMID 32316255, 2020). "In addition, CLA+ CD4+ TCM cells expressing CCR6+ or CCR4+ CXCR3+ negatively correlated with the severity of psoriasis." (PMID 31963581, 2020). "Interestingly, Th17 cells (a subset of CD4+ T cells), which play a crucial role in pathogenesis of psoriasis, exhibit a lower expression of clusterin and a higher expression of Bcl-2, which make them less susceptible to apoptosis." (PMID 32764517, 2020). "Follow‐up studies highlighted that intradermal injection of preactivated blood‐derived activated CD4+ T cells could induce active psoriasis in uninvolved skin from psoriasis patients." (PMID 32757303, 2020). "IL-17-producing CD4+ T cells, T helper 17 cells (Th17), were found to play a role in psoriasis." (PMID 32917058, 2020). "Psoriasis patients have a systemic presence of IL-17+ or IFN-γ+ T CD4 lymphocytes." (PMID 32801996, 2020). "Although the pathogenesis of psoriasis remains unclear, it has been widely recognized that T cells, especially CD4+ Th17 and IL-17-producing γδ T cells, play an important role in the development and progression of psoriasis 2, 3 and cutaneous DTH responses." (PMID 32929360, 2020). "In addition, psoriasis-like skin inflammation in animal models can be initiated by certain CD4+ T cells, and T cells can induce psoriatic lesions in human skin xenografts." (PMID 31402919, 2019). "Although there were few numbers of cells producing IL-17A or IFN-γ in PBS-injected control ears, significant accumulations of the IL-17A+ and IL-17A+IFN-γ+CD4+ T-cell populations were observed in the IL-23–injected ear, as observed in psoriatic dermis of patients with psoriasis." (PMID 29935220, 2019).
psoriasis (continued). "In addition to these effects, the number of CD4+ CD25+ Foxp3+ cells increased in the peripheral blood of psoriasis patients after treatment with biologicals." (PMID 31101850, 2019). "On the contrary, it was observed that, after stimulation with anti-CD3 and anti-CD28, there was a significant increase in CD4+ T cells of a regulatory phenotype (CD25hiFoxP3+LAP+) in untreated psoriasis patients compared with the group treated with methotrexate (p = 0.03)." (PMID 31101850, 2019). "As our data showed that IL-21 was highly expressed in psoriasis patients and promoted the proliferation of CD4+ T cells and the differentiation of Th17, we then investigated the proportion of Th17 and Treg cells in the PBMCs derived from psoriasis patients and healthy individuals." (PMID 31440249, 2019). "An imbalance between CD4+ Tregs and Th17 cells has been described in psoriasis." (PMID 31333659, 2019). "Previous studies have reported the multiple effects of IL-21 on CD4+ T cells in several diseases, so we hypothesized that IL-21 may also have effects on CD4+ T cells in psoriasis patients." (PMID 31440249, 2019). "For example, it was demonstrated that a psoriasis-like phenotype could be induced following adoptive transfer of dysregulated CD4+ T cells." (PMID 31019502, 2019). "Thus, psoriasis researchers became very quickly focused on characterizing CD4+ and CD8+ T cell responses in normal and diseased human skin." (PMID 31019502, 2019). "Thus, in the present study, we investigated the effects of IL-21 on CD4+ T cells of psoriasis patients." (PMID 31440249, 2019). "In addition, in psoriasis HIF1α is known to induce miR-210 overexpression at CD4+ T cells level mediated by TGF-β and IL-23." (PMID 30744173, 2019). "CD8+ T cells are also present in psoriasis, produce the same range of cytokines as CD4+ cells, and reside predominantly within the epidermis.Over the last decade, it has been shown that the main source of IL-17 in psoriasis is not T cells, but rather innate cells like neutrophils and mast cells." (PMID 31673756, 2019). "Indeed, studies have shown that in psoriasis, Treg suppression of pathologic effector CD4+ T cells is impaired." (PMID 30054515, 2018). "The immune synapse between DC and CD4+ T cells is central to the generation of harmful Th1 and Th17 responses in psoriasis; thus, the overall goal in modulating DC maturation and function in psoriasis is to limit the activation of adaptive immune responses which drive psoriatic inflammation." (PMID 29980703, 2018). "Given that esculetin induced CD4+Foxp3+ Tregs in IMQ-induced psoriasis-like mice, we further asked whether the effects of esculetin on skin lesion of the psoriatic mice were dependent on CD4+Foxp3+ Tregs." (PMID 30258447, 2018). "Traditionally, psoriasis has been thought to be mediated by CD4 lymphocytes." (PMID 28894119, 2017). "However, the same study found that the capability of Treg cells suppressing CD4+ T cells is impaired in patients with psoriasis." (PMID 29232931, 2017). "Methylation changes in naïve CD4+ T cells may affect CD4+ T cell polarization in psoriasis, indicating that perturbation of CD4+ T cell methylation may be critical for psoriasis pathogenesis." (PMID 27980695, 2016). "Suppression of NRIP1 in HaCaT cells could significantly inhibit cell growth and induce apoptosis, and the suppression of NRIP1 in CD4+ T cells isolated from psoriasis patients could downregulate the expression of RelA/p65 and decrease the secretion of IL-17." (PMID 27708240, 2016). "Psoriasis is an immune-mediated chronic inflammatory skin disorder that is characterized by abnormal interactions between keratinocytes and immune cells such as CD4+ T cells, resulting in keratinocyte hyperproliferation in the epidermis." (PMID 27980695, 2016). "All these results suggest that EGCG may regulate the immune function of psoriasis-like mice through the regulation of CD4+T cells and CD11c+ dendritic cells." (PMID 27581210, 2016).
psoriasis (continued). "On the other hand, extracellular deposition of ADAMTSL5, as observed in development, could also be responsible for stimulating antigen specific CD4+ T-cells (Th17 T-cells) that are also seen in psoriasis." (PMID 27857980, 2016). "In human psoriasis, the main producer of IL-17 is the CD4+T cell, namely the Th17 cell." (PMID 26691862, 2015). "In addition, DMF treatment has been shown to result in leukocytopenia and a reduction in the number of CD8+ and CD4+ T cells in psoriasis lesions, primarily due to apoptosis." (PMID 26246800, 2015). "Moreover, alefacept, in phase I and II clinical trials of psoriasis patients, demonstrated specific and significant depletion of CD2hi memory CD4+ T cells via NK cell-mediated ADCC and remission of their disease." (PMID 27110598, 2015). "Minor findings included increased numbers of CD3+ T cells and CD8+ T cells in the periadnexal area and in the deep dermis in DLE versus psoriasis lesional skin and CD4+ helper T cells at the DEJ and in periadnexal areas in DLE lesional skin versus normal and psoriasis lesional skin, respectively." (PMID 24744689, 2014). "Because TL1A is up-regulated in locally inflamed tissues in RA and psoriasis, we suspected that it might have a direct role on the controlling CD4 effector T-cells." (PMID 25148371, 2014). "The infiltration of dermal leucocytes in psoriasis consists predominantly of CD4+ and CD8+ T cells and may precede epidermal hyperplasia." (PMID 24062996, 2013). "In addition, we observed that ex vivo IL-9 stimulated the production of IL-17 by peripheral blood mononuclear cells or CD4+ T cells, especially in cells isolated from individuals with psoriasis." (PMID 23335955, 2013). "We first determined whether the CD4+ or CD8+ T cell distribution was altered in unaffected skin compared to lesional skin of psoriasis patients." (PMID 23468834, 2013). "Dysfunction of Treg in psoriasis might be related to level of CD127 expression in CD4+CD25+T cells separated in this study, and the restoration of dysfunctional CD4+CD25+T cells might be result of induction of CD127low CD4+CD25+T cells by photochemotherapy." (PMID 23365685, 2013). "In addition, we studied IL-9R expression in psoriatic skin lesions and on CD4+ T cells and the effect of IL-9 on IL-17A production in cultured human peripheral blood mononuclear cells or CD4+ T cells from psoriasis patients." (PMID 23335955, 2013). "Notably, IL-9-induced secretion of IL-17A and increase in IL-17A+CD4+ T cell numbers was greater for psoriasis patients than for normal healthy controls." (PMID 23335955, 2013). "Moreover, IL-9 significantly enhanced IL-17A production by cultured human peripheral blood mononuclear cells or CD4+ T cells, especially in psoriasis patients." (PMID 23335955, 2013). "A growing body of evidence suggests that CD4+Th17 contribute to the pathogenesis of psoriasis." (PMID 23365685, 2013). "In α2/β1 integrin double-transgenic mice, skin irritation led to a chronic condition resembling psoriasis with persistent hyperplasia, cutaneous influx of CD4+ and CD8+ T-lymphocytes and secretion of pro-inflammatory cytokines like TNF-α, IFN-γ, IL-1β and IL-6." (PMID 22590584, 2012). "This additionally clarified the significant role of CD4+ T cells in the onset of psoriasis." (PMID 22545055, 2012). "As HIV-1 infection progresses and CD4+ T cell counts decrease, psoriasis can worsen." (PMID 22577363, 2012). "CD4+CD127lowCD25highFoxp3+ regulatory T cells (nTreg) play critical role in the suppression of excessive inflammatory response in various diseases including psoriasis." (PMID 23251632, 2012). "Furthermore, the differentiation of Th17 cells, which play an important role in the development of psoriasis, was suppressed by plasma treatment, suggesting that plasma may be useful for treating CD4+ T cell-mediated autoimmune diseases, such as psoriasis." (PMID 41614914, 2026).